FASN (fatty acid synthase)
Diseases named in the same sentence as FASN in open-access papers (continued):
Sharing a sentence is not in itself a finding about the gene and the disease.
HIV-1 infection (2 papers, 2017 to 2025). The type species of lentivirus and the etiologic agent of acquired immunodeficiency syndrome (AIDS). "To determine if HIV-1 infection also causes FASN relocalization, we used immunofluorescence to monitor FASN distribution in HIV-1 infected TZM-bl cells." (PMID 28962653, 2017). "More recently, we reported that HIV-1 infection upregulated FASN protein levels in vitro, whereas siRNA-mediated FASN knockdown, or treatment with FASN inhibitors (e.g., Fasnall or C75), reduced virion production." (PMID 40558086, 2025). "Here we show that HIV-1 infection increases FASN expression, and using both siRNA and pharmacological tools, we show that FASN inhibition blocks a late stage of HIV-1 replication." (PMID 28962653, 2017). "Our in vitro results show that HIV-1 infection increases intracellular FASN levels in both TZM-bl and SupT1 cells." (PMID 28962653, 2017). "Here we report that HIV-1 infection increases host fatty acid synthase (FASN) levels, and a decrease in FASN activity attenuates HIV replication during a late stage of its replication cycle." (PMID 28962653, 2017). "Using purinome capture media, we observed that HIV-1 infection increases intracellular levels of fatty acid synthase (FASN), a NADPH-using enzyme critical to the synthesis of de novo fatty acids." (PMID 28962653, 2017). "Here we have shown that HIV-1 infection increases FASN expression." (PMID 28962653, 2017). "Western blotting with a FASN-specific antibody confirmed that HIV-1 infection increases FASN levels twofold to fivefold, as early as 24 h post infection; similar increases in FASN protein levels were also observed following HIV-1 infection of SupT1 and THP-1 cells." (PMID 28962653, 2017). "Thus, our results are consistent with previous in vitro and in vivo studies that correlated HIV-1 infection with increased FASN levels." (PMID 28962653, 2017). "To validate the purinome-capture of FASN, we measured FASN expression in TZM-bl cells 24 and 48 h post HIV-1 infection." (PMID 28962653, 2017). "Thus, similar to HCV, HIV-1 infection does not cause intracellular FASN redistribution." (PMID 28962653, 2017). "FASN mRNA levels, normalized to 18S rRNA, did not change following HIV-1 infection, suggesting FASN regulation in TZM-bl cells occurs post-transcriptionally." (PMID 28962653, 2017). "When FASN activity is inhibited in the context of HIV-1 infection, HIV-1 Gag is produced but viral particles are not released into the culture supernatant." (PMID 28962653, 2017). "FASN knockdown or inhibition did not reduce intracellular levels of HIV-1 Gag protein, indicating that FASN is required for a late-stage process of HIV-1 infection." (PMID 40558086, 2025).
hyperthyroidism (2 papers, 2006 to 2022). Overactivity of the thyroid gland resulting in overproduction of thyroid hormone and increased metabolic rate. "Contrasting with the push for lipolysis, hyperthyroidism induces down regulation of adipose fatty acid synthase and lipoprotein lipase; most of these effects reversed in hypothyroidism." (PMID 16472384, 2006).
hypothyroidism (2 papers, 2006 to 2024). Abnormally low levels of thyroid hormone. "In mice, mild hypothyroidism brought about by dietary iodine restriction, results in elevated hepatic expression of lipid utilization genes including ACACA, FASN, and CD36." (PMID 38658325, 2024).
influenza (2 papers, 2020 to 2021). An acute viral infection of the respiratory tract, occurring in isolated cases, in epidemics, or in pandemics; it is caused by serologically different strains of viruses (influenzaviruses) designated A, B, and C, has a 3-day incubation period, and usually lasts for 3 to 10 days. "Although previous reports have documented the regulation of lipid synthesis by influenza infection, we identifies NS1 as the viral protein that mediates this effect through the cellular partner FASN." (PMID 32415096, 2020).
intellectual disabilities (2 papers, 2022 to 2024). "Whereas global (whole body) fatty acid synthase-null mutants die in utero, and mutations or heterozygote removal of fatty acid synthase results in significant intellectual disabilities." (PMID 38183680, 2024). "Previous work identified high levels of FASN RNA expression in APs of the human developing cortex and showed that enhanced FASN activity, caused by a human variant associated with intellectual disability, affects progenitor-cell activity." (PMID 34996870, 2022). "A recessive point variant in the human FASN gene, causing an enzymatic gain of function, has been associated with intellectual disability and affects NPCs." (PMID 34996870, 2022).
ischemia (2 papers, 2017 to 2023). A hypoperfusion of the BLOOD through an organ or tissue caused by a PATHOLOGIC CONSTRICTION or obstruction of its BLOOD VESSELS, or an absence of BLOOD CIRCULATION. "By subjecting mouse primary astrocyte into OGD model, we confirmed again that FASN-driven lipogenesis was spontaneously promoted after ischemia injury in astrocytes." (PMID 37968698, 2023).
kidney tumours (2 papers, 2021 to 2023). "They found lower expression of the gene fatty acid synthase (FASN) in people who were obese; FASN encodes the enzyme fatty acid synthase that making fatty acids – an essential source of energy; the altered gene expression may have led to slower-growing kidney tumours." (PMID 34014795, 2021). "All these data suggest that FASN plays a key role in ccRCC carcinogenesis and that the FASN expression level could be equally used as a predictor of poor prognosis in both pediatric and adult renal tumors." (PMID 36834678, 2023).
lipodystrophy (2 papers, 2010 to 2023). A congenital or acquired disorder characterized by abnormal loss or redistribution of the adipose tissue in the body. "Patients with lipodystrophy, in which distribution of HCV co-infected patients was identical to that of the whole group, also showed similar serum FASN concentrations [9.7 (3.2) μg/L] with respect to patients without such condition [10.4 (4.1) μg/L]." (PMID 20707918, 2010).
mastitis (2 papers, 2017 to 2023). Inflammation of breast tissue during lactation or postpartum due to an obstructed duct or infection. "The expression of FASN was negatively affected by mastitis, whereas TZD treatment prevented a decrease in expression of FASN but delayed the increase in expression of LPL in mastitis-treated goats after IMI." (PMID 28740504, 2017).
mesothelioma (2 papers, 2021 to 2022). A usually malignant and aggressive neoplasm of the mesothelium which is often associated with exposure to asbestos. "High expression of FASN was related to poor OS outcomes in ACC (p = 0.015), BLCA (p = 0.0044), CESC (p = 0.004), HNSC (p = 0.045), KIRC (p = 3.9e-06), KIRP (P = 0.017), MESO (Mesothelioma) (P = 0.0043), LGG (P = 0.0035), and SARC (P = 0.018)." (PMID 34879004, 2021).
mucinous tumor (2 papers, 2020). "Our rationale for utilizing orlistat was that it inhibits FASN (required for MUC2 secretion) which would induce ERS, while at the same time reducing mucinous tumor growth." (PMID 32811515, 2020).
myocardial infarction (2 papers, 2022 to 2023). Gross necrosis of the myocardium, as a result of interruption of the blood supply to the area, as in coronary thrombosis. "Lipid metabolism and small molecule transport-related pathways, such as the fatty acid metabolic process, the external side of the plasma membrane and the fatty acid synthase activity, were enriched in dilated cardiomyopathy and myocardial infarction." (PMID 37056578, 2023). "For example, myricetin alleviates MIRI by up-regulating COX-2 and cytochrome P450 and p38, and downregulating fatty acid synthase antibody and glucose 6-phosphatedehydrogenase signaling pathway, thus reducing myocardial infarction, apoptosis, inflammation response, and oxidative stress." (PMID 35268807, 2022).
Nephroblastoma (2 papers, 2013 to 2025). An embryonal neoplasm characterized by the presence of epithelial, mesenchymal, and blastema components. "The results showed that high expression of FASN in nephroblastoma is associated with poor prognosis, and it is believed that FASN can serve as a prognostic biomarker for nephroblastoma patients." (PMID 41480378, 2025). "Also, the level of FASN expression in this model of Wilms tumor was only moderately increased, which suggests that PET/CT imaging with radiolabeled acetate and choline may not be suitable for detection and therapy monitoring in this Wilms tumor model." (PMID 22875335, 2013).
neutropenia (2 papers, 2020 to 2024). A decrease in the number of neutrophils found in the blood. "Genetic inducible knockout of FASN (fatty acid synthase) in bone marrow results in severe neutropenia by specifically reducing the levels of PC within the endoplasmic reticulum of granulocytes, therefore leading to CHOP-mediated ER stress response and massive neutrophil cell death." (PMID 32178254, 2020).
nonalcoholic fatty liver (2 papers, 2022 to 2024). "Our mechanic studies indicated that L-theanine can regulate lipid metabolism of nonalcoholic fatty liver through activating Ca2+-CaMKKβ-AMPK signaling pathway, inhibit the expression of ACC1, FASN and PPARγ which were related to fatty acid synthesis." (PMID 35428314, 2022).
pancreatic neuroendocrine tumor (2 papers, 2025). Pancreatic endocrine tumor, also known as pancreatic neuroendocrine tumor (PNET), describes a group of endocrine tumors originating in the pancreas that are usually indolent and benign, but may have the potential to be malignant. "FTO-induced APOE activates the PI3K/AKT/mTOR signaling pathway by regulating the ubiquitination state of FASN, which enhances lipid metabolism and proliferative capacity, thereby promoting the malignant progression of pancreatic neuroendocrine tumors." (PMID 40764609, 2025). "In contrast, in pancreatic neuroendocrine tumors, FTO promotes malignancy by enhancing APOE expression through FASN‐mediated lipid metabolism, suggesting an oncogenic role." (PMID 41141648, 2025). "Fatty acid-binding protein 5 regulates the expression of FASN through the ubiquitin–proteasome pathway, activates the WNT/β-catenin signaling pathway, and modulates lipid metabolism to promote the progression of pancreatic neuroendocrine tumors." (PMID 40764609, 2025).
pulmonary arterial hypertension (2 papers, 2021 to 2023). Pulmonary arterial hypertension (PAH) is a group of diseases characterized by mean pulmonary artery pressure >20 mmHg and elevated pulmonary arterial resistance leading to right heart failure. "This study is aimed at examining whether fatty acid synthase (FAS) can regulate mitochondrial function in hypoxia-induced pulmonary arterial hypertension (PAH) and its related mechanism." (PMID 34457121, 2021).
renal fibrosis (2 papers, 2020 to 2025). A final common manifestation of a wide variety of chronic kidney diseases characterized by glomerulosclerosis and tubulointerstitial fibrosis. "Western blotting and immunohistochemical analysis showed that NF significantly induced TNF-α, CD36, SREBP-1/2, and acetyl-CoA carboxylase expression and renal fibrosis, and reduced fatty acid synthase and AMPK compared to other groups (p < 0.05)." (PMID 32575412, 2020). "In mesangial cells, high glucose enhances ChREBP O-GlcNAcylation and upregulates renal acetyl-CoA carboxylase (ACC) and fatty acid synthase (FASN) to exacerbate lipid toxicity, prompting HIF-1α to further intensify renal fibrosis." (PMID 40852041, 2025).
retinoblastoma (2 papers, 2017 to 2018). A malignant tumor that originates in the nuclear layer of the retina. "Fatty acid synthase (FASN) has a higher expression in retinoblastoma (RB) than that in normal cells, and is associated with high invasive ability." (PMID 28187442, 2017). "Important mediators of the insulin pathway such as Akt, BCL-2 antagonist of cell death (BAD), FOXO1, and FASN were found to be phosphorylated in both retina and retinoblastoma tissues." (PMID 29914080, 2018).
serous carcinoma (2 papers, 2010 to 2020). "Multivariate analysis showed that an FASN staining score of >1 in serous carcinomas was associated with a worse overall survival time (P < .01)." (PMID 20508725, 2010). "It has been reported that the expression of FASN is increased in high grade serous carcinomas and its overexpression is correlated with poor outcome for women with OC32,33." (PMID 31932581, 2020). "After adjusting for age, stage, and race in a multivariate analysis, we found that, in patients with primary serous carcinomas, FASN expression remains an independent marker for prognosis with a hazard ratio of 1.87 (95% CI: 1.12–3.11, P = .02)." (PMID 20508725, 2010). "Moreover, we found that recurrent serous carcinomas exhibited higher FASN immunointensities than their matched primary tumors (P < .001)." (PMID 20508725, 2010). "Analyzing 162 high-grade serous carcinomas showed a significant positive correlation in NAC1 and FASN immunointensities (P < .0001, Fisher Exact test)." (PMID 20508725, 2010).
skin cancer (2 papers, 2022). "FASN plays an important role in the occurrence of skin cancer." (PMID 35791446, 2022).
small cell lung carcinoma (2 papers, 2022). Small cell lung cancer (SCLC) is a highly aggressive malignant neoplasm, accounting for 10-15% of lung cancer cases, characterized byrapid growth, and early metastasis. "Besides ACLY and OGDH, fatty acid synthase (FASN) was recently identified as a novel substrate of USP13 in small cell lung cancer (SCLC)." (PMID 36188217, 2022).
uveal melanoma (2 papers, 2023 to 2025). A melanoma derived from melanocytes of the uveal tract. "We then determined that inhibitors of FASN and mTOR led to the suppression of uveal melanoma cell growth." (PMID 37444561, 2023). "We aimed to identify unique metabolic features between uveal melanoma and normal uveal melanocytes and found that uveal melanoma cells expressed elevated levels of enzymes involved in lipid/fat metabolism such as fatty acid synthase (FASN)." (PMID 37444561, 2023). "For instance, in uveal melanoma, enzymes involved in fatty acid synthesis, such as Fatty Acid Synthase (FASN), and in fatty acid oxidation, like Acyl-CoA Dehydrogenase (ACAD), are upregulated, supporting enhanced lipid metabolism and providing energy to the rapidly proliferating tumor cells." (PMID 40607060, 2025).
ZIKV infection (2 papers, 2022 to 2023). "Moreover, recent results demonstrated lipid remodeling through SREBPs and increased FASN expression in human dendritic cells during ZIKV infection." (PMID 36882750, 2023). "Interestingly, obvious decreases in SCD1 and FASN levels were observed 24 h after ZIKV infection, compared with the mock levels, but no significant change in ACC1 or ATGL level was observed." (PMID 36405969, 2022).
abortion (1 paper, 2025). the ending of pregnancy by removing a fetus or embryo before it can survive outside the uterus. "The spontaneous-abortion-prone model gave further evidence that FK506 exerted a protective effect on pregnancy by regulating the FASN-CEACAM1 axis." (PMID 40046057, 2025).
acute coronary syndrome (1 paper, 2013). Signs and symptoms related to acute ischemia of the myocardium secondary to coronary artery disease. "Simultaneously, emerging evidences have implicated the association between fatty acid synthase (FAS) and acute coronary syndrome (ACS)." (PMID 23305094, 2013).
acute promyelocytic leukemia (1 paper, 2021). An aggressive form of acute myeloid leukemia (AML), characterized by arrest of leukocyte differentiation at the promyelocyte stage, due to a specific chromosomal translocation t(15;17) in myeloid cells. "Accordingly, FASN levels decreased during all-trans retinoic acid (ATRA)-mediated granulocytic differentiation of acute promyelocytic leukemia (APL) cells, partially via autophagic degradation." (PMID 33742137, 2021).
adrenocortical carcinoma (1 paper, 2021). "Advanced adrenocortical carcinoma is a devastating disease with limited therapeutic options; FASN as a potential druggable target warrants further studies." (PMID 34285285, 2021). "FASN as a potentially druggable target for treatment of the devastating disease adrenocortical carcinoma warrants further studies." (PMID 34285285, 2021).
alcoholic cirrhosis (1 paper, 2024). "Escherichia Shigella has been shown to aggravate alcoholic cirrhosis, whereas in Tibetan sheep Escherichia_Shigella was significantly correlated with stearic acid and FASN gene expression in the 3.5-year-old group." (PMID 38472792, 2024).
anaplastic astrocytoma (1 paper, 2020). "Similar findings were obtained for the FASN+/CD63+ EV population in anaplastic astrocytoma patients (mean 2.9 × 105/mL AA vs 5.8 × 104/mL HD, P = 0.005) as well as for the FASN+/CD81+ EV population (mean 5.2 × 105/mL AA vs 2.3 × 105/mL HD, P = 0.03)." (PMID 32178271, 2020).
aortic atherosclerosis (1 paper, 2025). A atherosclerosis that involves the aorta. "Inhibition of circulating fatty acid synthase with platensimycin reduces foam cell formation in vitro and decreases aortic atherosclerosis in ApoE-deficient mice, highlighting its potential as a therapeutic target." (PMID 39972116, 2025).
aristolochic acid nephropathy (1 paper, 2025). "The present study identified LDH, involved in aerobic respiration, FASN, related to fatty acid beta-oxidation, and ATP synthase as targets directly affected by aristolochic acid nephropathy." (PMID 40827445, 2025).
astrocytic tumor (1 paper, 2019). A glial tumor of the brain or spinal cord showing astrocytic differentiation. "Finally, TVB- 2640 compound is one of the first bioavailable fatty acid synthase (FASN) inhibitor to enter clinical trials for breast, colon, and astrocytic tumors, in combination with chemotherapy with the aim of enhancing clinical responses and prolonging stable disease times (NIH)." (PMID 31921661, 2019).
autism (1 paper, 2014). Persistent deficits in social interaction and communication and interaction as well as a markedly restricted repertoire of activity and interest as well as repetitive patterns of behavior. "The apoptotic marker soluble fatty acid synthase antigen was reported to be high in Saudi children with severe autism, and can be considered an indicator of disease severity." (PMID 24708718, 2014).
autoimmune hepatitis (1 paper, 2022). Hepatitis caused by autoantibodies. "In autoimmune hepatitis (AIH), some of the VDR and CTLA4 variants are involved in triggering the immune process, these genotype variants being linked with fatty acid synthase (FAS) promoter variants or pro-inflammatory cytokines that are part of the TNF superfamily." (PMID 36077185, 2022).
benign ovarian tumors (1 paper, 2020). "Compared to normal controls, borderline and benign ovarian tumors, the urinary Cerulenin was down-regulated in OC, which is a fatty acid synthase inhibitor that induce tumor cell apoptosis." (PMID 33291756, 2020).
benign prostatic hyperplasia (1 paper, 2021). A non-cancerous nodular enlargement of the prostate gland. "Furthermore, differential quantitative proteomic analysis of patients with PCa and benign prostatic hyperplasia (BPH) showed a significant decrease in FKBP5, FAM129A, RAB27A, FASN, NEFH proteins after local PCa treatment." (PMID 33810357, 2021).
brain cancer (1 paper, 2024). A primary or metastatic malignant neoplasm affecting the brain. "In the context of a tumor, brain cancer cells overexpress the fatty acid synthase (FASN) to synthesize new FAs to sustain their growth." (PMID 38893165, 2024).
cardiomyopathy (1 paper, 2019). A disease of the heart muscle or myocardium proper. "Similar gene expression patterns were observed in the cluster of cardiomyopathy genes (GNAs, MTHFR, CREBs, and FASN)." (PMID 30650650, 2019).